P2RY10 (P2Y receptor family member 10)
Description:
Putative receptor for purines coupled to G proteins.
Synonyms: P2Y10; LPS2; LYPSR2
Tractability: Small molecule: a structure with a bound ligand is known; a high-quality ligand is known; it belongs to a druggable protein family. Antibody: its Gene Ontology location is reachable by antibodies, with high confidence; UniProt places it where antibodies can reach, with medium confidence; UniProt predicts a signal peptide or a membrane-spanning region. PROTAC: a small molecule that binds it is known.
Target class: Family A G protein-coupled receptor; Membrane receptor
Chemical probes: CHEMBL3577182
Gene: Protein-coding gene on chromosome X (78,945,332 to 78,963,727, forward strand). Ensembl gene ENSG00000078589.
Subcellular location: Cell membrane
Pathways (Reactome):
Signal Transduction: G alpha (q) signalling events; P2Y receptors
Gene Ontology:
Molecular function: G protein-coupled receptor activity
Biological process: G protein-coupled receptor signaling pathway
Cellular component: plasma membrane; membrane
Homologues: Orthologues: chimpanzee P2RY10 (99% identical), macaque P2RY10 (98% identical), dog P2RY10 (90% identical), rabbit P2RY10 (88% identical), pig P2RY10 (88% identical), rat P2ry10 (84% identical), mouse P2ry10 (83% identical), guinea pig P2RY10 (81% identical), tropical clawed frog p2ry10 (57% identical), zebrafish p2ry10 (52% identical). Paralogues in human: GPR17 (31% identical), LPAR4 (28% identical), CYSLTR1 (27% identical), LPAR6 (27% identical), F2RL1 (25% identical), P2RY8 (24% identical), F2RL3 (24% identical), GPR35 (24% identical), GPR18 (23% identical), GPR65 (23% identical), F2R (23% identical), GPR20 (23% identical), and 4 more.
Diseases named in the same sentence as P2RY10 in open-access papers:
P2RY10 is named in the same sentence as 20 diseases in open-access papers, as found by Europe PMC text mining. Sharing a sentence is not in itself a finding about the gene and the disease. The quoted sentences say what the papers report.
colitis (2 papers, 2022 to 2025). Inflammation of the colon. "P2ry10−/− mice infected with C. rodentium showed more severe colitis, more rapid weight loss and more bacteria load in colons." (PMID 40845099, 2025). "We observed that P2ry10−/− ILCs were less effective than P2ry10+/+ ILCs on protecting NSG mice and clearing C. rodentium, displaying more severe colitis, increased weight loss, and higher bacteria load." (PMID 40845099, 2025). "We observed lower Gpr174 expression in colonic Treg cells, and P2ry10 and P2ry10b deficiency in CD4+ T cells prevents LysoPS-dependent colitis exacerbation." (PMID 35608941, 2022). "Because colonic Treg cells expressed P2ry10 and LysoPS affected glycolytic metabolism in in vitro–skewed Treg cells, we analyzed the impact of LysoPS on the suppressive activity of Treg cells in this colitis model." (PMID 35608941, 2022). "LysoPS-induced aggravation of colitis was impaired in mice lacking P2ry10 and P2ry10b, and their CD4+ T cells were hyporesponsive to LysoPS." (PMID 35608941, 2022). "Lack of P2ry10 and P2ry10b provided lower responsiveness to LysoPS for CD4+ T cells, which led to suppression of LysoPS-dependent aggravation of colitis." (PMID 35608941, 2022).
coronary artery disease (1 paper, 2022). "P2RY10 expression is increased in the synovial tissue and peripheral blood from patients with rheumatoid arthritis and coronary artery disease, respectively." (PMID 35608941, 2022).
Hypertension (1 paper, 2025). The presence of chronic increased pressure in the systemic arterial system. "Although there is currently no research reporting the association of the genes P2RY10, GPR171, KLC3, and LYSMD3 with hypertension, these genes may indirectly affect the occurrence of hypertension." (PMID 39854379, 2025).
lung carcinoma (1 paper, 2020). "Next, we determined the expression levels of P2X sub-families P2RX1–7 and P2Y receptors P2RY1, P2RY2, P2RY4, P2RY5 (LPAR6), P2RY6, P2RY7 (LTB4R), P2RY8, P2RY9 (LPAR4), P2RY10–14 in normal lung tissues and lung cancer tissues." (PMID 32638267, 2020).
metastatic melanoma (1 paper, 2021). A melanoma that has spread from its primary site to another anatomic site. "P2RY10 has been reported to be a tumor microenvironment-associated gene and a potential diagnostic biomarker of metastatic melanoma." (PMID 34367245, 2021).
sarcoma (1 paper, 2020). A usually aggressive malignant neoplasm of the soft tissue or bone. "Three hub genes (CD48, P2RY10, and RASAL3) associated with immunotherapy and the development of sarcomas were analyzed and presented, as potential prognostic biomarkers and/or therapeutic targets of immunotherapy for sarcomas." (PMID 33292275, 2020). "In addition, immunohistochemistry (IHC) staining data acquired from the HPAD also confirmed the differential expression of the predicted genes (CD48, P2RY10, RASAL3) in sarcoma samples." (PMID 33292275, 2020).
Sepsis (1 paper, 2025). Sepsis is defined as life-threatening organ dysfunction caused by a dysregulated host response to infection. "Moreover, in the GSE137340 validation group, the levels of CD3E, CD40LG, FCER2, and P2RY10 expressions were markedly reduced in the sepsis group when contrasted with the control group (P < 0.05)." (PMID 40129981, 2025).
cancer (1 paper, 2022). A tumor composed of atypical neoplastic, often pleomorphic cells that invade other tissues. "An example of a GPCR not previously linked directly to cancer was the P2Y receptor family member 10 (P2RY10), found in the first Pareto front." (PMID 36513718, 2022). "Our approach was confirmed by re-discovery of established cancer targets such as the LPA and mGlu receptor families, but also discovered novel GPCRs which had not been linked to cancer before such as the P2Y Receptor 10 (P2RY10)." (PMID 36513718, 2022).
P2RY10 also shares sentences with these, for which no sentence is quoted: atherosclerosis (2 papers); infection (2); tumor (2); asthma (1); autoimmune disease (1); colorectal cancer (1); COVID-19 (1); Crohn disease (1); experimental autoimmune encephalomyelitis (1); inflammatory bowel disease (1); rheumatoid arthritis (1); Rotavirus infection (1).